ALK (ALK receptor tyrosine kinase)
Diseases named in the same sentence as ALK in open-access papers (continued):
Sharing a sentence is not in itself a finding about the gene and the disease.
tumor (continued). "The genesis of the tumor is linked to genetic anomalies, including those related to the ALK gene (anaplastic lymphoma kinase); nonetheless, some cases are not ALK-positive, indicating genetic variability." (PMID 39105041, 2024). "Additionally, alternative ALK vaccines utilizing peptides or lipid vesicles encapsulating ALK antigens showcased potential in restraining tumor advancement in preclinical models." (PMID 38397899, 2024). "Next, we examined how changing WNT signaling impacts the growth of MYCN and ALK/MYCN tumor cells." (PMID 38451815, 2024). "Liquid biopsy is unable to assess tumors morphologically; thus, the quantity of ALK-positive cells in the primary tumor may have been relatively low." (PMID 39781173, 2024). "While MYCN and mutant anaplastic lymphoma kinase (ALKF1174L) cooperate in tumorigenesis, how ALK contributes to tumor formation remains unclear." (PMID 38451815, 2024). "We discovered a mechanism to increase the surface display of the ALK target on tumour cells." (PMID 38877641, 2024). "Periostin, however, appears to be the primary ECM that influences ALK-driven tumor biology." (PMID 38451815, 2024). "ALK autophosphorylation and phosphorylation of STAT3 are inhibited by aletcinib, also aletcinib could suppress the development of EML4-ALK-positive tumor cells." (PMID 38234663, 2024). "Interestingly, the authors observed that CD147 contributes to the survival and proliferation of ALK+ ALCL cells in vitro and to engraftment and tumor growth in vivo in an ALK+ ALCL-xenotransplant mouse model." (PMID 39273126, 2024). "Consequently, patients harboring EGFR mutations or ALK rearrangements demonstrated a diminished PD-L1 and CD8 co-expression level in the tumor microenvironment, potentially contributing to an inadequate response to ICIs." (PMID 38397899, 2024). "It is likely that extensive prior therapies accelerate tumor evolution and promote the selection of particularly aggressive cell clones, which could diminish response to ALK inhibition." (PMID 38168093, 2024). "The FISH result was estimated to be caused by structural variants affecting the 5′ binding site, associated with higher genomic instability of the tumor typical for prolonged smoking; therefore, it likely did not represent true ALK rearrangement." (PMID 39125737, 2024). "The treatment of this type of tumor includes systemic therapies such as chemotherapies or anti-inflammatories; in recent years, targeted anti-ALK therapies have emerged and became the standard of care in ALK rearranged patients." (PMID 39931211, 2024). "A small part of the tumor cells may display alterations of the ALK locus, but its clinical significance and targetability by TKIs remains questionable." (PMID 39125737, 2024). "Furthermore, a patient with an ALK‐rearranged tumor achieved a remarkable 3‐year progression‐free survival following crizotinib treatment." (PMID 38661052, 2024). "EMT, the process by which epithelial cells acquire mesenchymal features, is associated in cancer with tumor invasion, initiation, metastasis, and resistance to therapy, notably with EGFR and ALK inhibitors in EGFR-mutation-positive and ALK-fusion-positive NSCLC models." (PMID 39301544, 2024). "Because the tumor findings, PDC NGS analysis, and PDC drug sensitivity test suggested both ALK-positive cells and BRAF-mutated malignant cells, the combined effect of an ALK-TKI and a BRAF inhibitor was tested on the PDC." (PMID 38398169, 2024). "Tumours with EGFR, ALK, BRAF mutations may be resistant to PD-1/PD-L1 immunotherapy, and are more suitable for targeted therapy or combination therapy." (PMID 39530091, 2024). "Consequently, 2nd and 3rd generation ALK inhibitors that can cross the blood-brain barrier and show marked intracranial anti-tumor activity in advanced ALK-positive patients have been developed." (PMID 38927911, 2024).
tumor (continued). "A variety of ALK inhibitors are available, including crizotinib, ceritinib, lorlatinib, alectinib, entrectinib and brigatinib, that can downregulate the STAT3 pathway in patients with ALK-positive pcALCL, thereby causing apoptosis among tumour cells." (PMID 38337516, 2024). "We hypothesized that ALK rearrangements may contribute to an immunophenotype of APH tumor cells similar to that of spindle cells expressing myogenic markers within IMT." (PMID 39867882, 2024). "However, examining the molecular underpinnings of ALK oncogene dependence, scientists pinpointed the RAS-RAF-MEK-ERK pathway as essential for the survival of ALK+ tumor cells." (PMID 38397899, 2024). "Inhibition of FAK in ALK/MYCN tumor cells increased GSK3β activity." (PMID 38451815, 2024). "These genes and the pathways in which they reside could play a role as tumour suppressors in signalling pathways that sensitise NB to ALK inhibitors, thereby representing potential therapeutic targets for drug combinations." (PMID 38653965, 2024). "ALK vaccine pairing with ALK-TKIs notably delayed tumor relapse post-TKI treatment." (PMID 38397899, 2024). "Several oncogenic signaling pathways, such as Akt/mTOR, JAK/STAT3, and EGFR/MAPK, or the loss or silencing of PTEN, ALK, and EGFR, are involved in the regulation of PD-L1 transcription, potentially leading to the upregulation of PD-L1 expression in tumor cells." (PMID 38762484, 2024). "Limited tumor molecular testing at the time of diagnosis revealed an ALK—ELM4 fusion by IHC." (PMID 38196737, 2024). "Indeed, treatment with CHIR99021 significantly increased EdU incorporation in ALK/MYCN POSTN sgRNA tumor cells." (PMID 38451815, 2024). "Interestingly, a novel thrombospondin 1 (THBS1) fusion with ALK (THBS1::ALK fusion) was identified through next-generation sequencing, providing new molecular insight into the pathogenesis of this rare tumor." (PMID 39171208, 2024). "This may explain the significant changes in the morphological structure and biological behavior of tumor cells when ALK is rearranged with these genes." (PMID 39281378, 2024). "Different types of integration of EML4 with ALK or other genes, the presence of a secondary mutation in ALK, and activation of alternative signaling pathways such as EGFR, are the mechanisms by which tumor cells become resistant." (PMID 38234663, 2024). "Like other therapies, there are mechanisms that make tumor cells resistant to ALK inhibitors." (PMID 38234663, 2024). "Advancements in the understanding of the indolent nature of the tumor have allowed for more conservative treatment approaches, such as reexcisions, radiotherapy, and recently, the use of ALK inhibitors, instead of the total laryngectomy that was used as a treatment option 25 years ago." (PMID 39171208, 2024). "If the tumor shows ALK rearrangement, ALK inhibitors, such as Crizotinib, might be considered as a treatment option." (PMID 38310322, 2024). "Overexpression of ABCB1 has been demonstrated in tumor samples obtained from patients whose tumors have developed resistance to the ALK inhibitor ceritinib in the absence of secondary ALK mutations." (PMID 37840856, 2023). "The tumor microenvironment of ALK-positive NSCLC has been demonstrated to be immunosuppressive." (PMID 37822928, 2023). "Importantly, the regulatory authorizations for ALK inhibitors are for neoplasms bearing ALK fusions/rearrangements and, in those conditions, response rates are usually in the range of 50–85%." (PMID 37773318, 2023). "If SHP2 inhibition combines synergistically with ALK inhibition to reduce tumour cell growth, then SHP2 inhibitors might improve outcomes with alectinib in ALK+ NSCLC at sub-toxic doses of SHP2 inhibition." (PMID 37339995, 2023).
tumor (continued). "Adjuvant atezolizumab or pembrolizumab are not recommended in patients with tumours containing EGFR mutations or ALK translocations based on lack of efficacy in the advanced disease setting." (PMID 37999109, 2023). "We speculate that these tumor types may be composed of heterogenic (but dominantly EGFR- or ALK-mutant) cancer cells that are prone to significant treatment response with targeted therapies." (PMID 37768380, 2023). "Such ALK-MYCN positive feedback loops converge on sustained tumor growth." (PMID 37765276, 2023). "Whereas we encountered a patient with a leukemic presentation of a small cell variant whose circulating small tumor cells exhibited low expression of CD30 and ALK on immunohistochemistry and flow cytometry, with only one-tenth of NPM-ALK mRNA expression compared to large tumor cells." (PMID 38136278, 2023). "The tumor-to-blood ratio in H2228 xenografts could be reducedby pretreatment with ALK inhibitor crizotinib." (PMID 37647220, 2023). "In some circumstances, LB may replace tissue tumour biomarker analysis, and ALK profiling in circulating tumour DNA (ctDNA) may serve as a treatment guiding tool." (PMID 36571695, 2023). "Among 128 patients tested, 16 (12.5%) had EGFR mutations detected with either technique by formalin-fixed paraffin-embedded (FFPE) tumor tissue or/and serum circulating tumor DNA using next-generation sequencing, and 6 (4.7%) had ALK rearrangement by FFPE tumor tissue." (PMID 37009936, 2023). "With respect to OS according to smoking status, univariate analysis showed that in never-smokers with aged <75 years, male sex, ECOG PS 0-2, stage IV disease, primary tumour location over the upper lobe, and ALK-TKI treatment had better OS than did their smoker counterparts." (PMID 37007097, 2023). "Likewise, the eXalt2, a Phase I/II study, reported a concordance rate of 91% between tumor tissue and liquid biopsy in patients with ALK rearrangements." (PMID 37445976, 2023). "The poor immune response to ALK is therefore related to the specific location of the tumours, and other recent work suggests that this might be due to poor priming of T cells specifically in lung cancer." (PMID 37795653, 2023). "Therefore, to potentially complement sNGS, we validated the Idylla Genefusion assay for ALK, ROS1, and RET rearrangements and MET exon 14 skipping variant detection using 34 tumor samples that were previously orthogonally tested via FISH and NGS." (PMID 37628603, 2023). "Similarly, John R. Goldblum and colleagues reported a high frequency (9/11) of ALK positivity in AFH, which is an EWSR1 (or rarely FUS) rearrangement-associated neoplasm characterized by accompanying lymphoplasmacytic infiltrate." (PMID 37120571, 2023). "Moreover, despite an initial benefit of the targeted drug in molecularly well-defined tumors, patients inevitably experience tumor progression due to the development of resistance (i.e., Crizotinib in ALK-rearranged NSCLC population and CNS relapses)." (PMID 36839989, 2023). "PD-1 inhibitors play an important role in the treatment of patients with mNSCLC and, alongside their development, predictive biomarker testing for tumour genomic aberrations in such genes as EGFR or ALK, and PD-L1 expression have become mandatory in most European countries." (PMID 37386452, 2023). "IGF-1R inhibitors sensitize tumor cells to the effects of ALK inhibition." (PMID 37773318, 2023). "The results of preclinical studies showed that it could effectively inhibit proliferation of crizotinib-sensitive or -resistant tumor cell lines, and ALK-positive crizotinib-sensitive or -resistant tumor growth in mouse models (data unpublished)." (PMID 36829154, 2023). "On the other hand, the tumour monitoring value of circulating cytokine markers in ALK + NSCLC has yet to be explored and remains unclear." (PMID 37120670, 2023). "ALK expression was strong in tumor cells with two different antibody clones, 1A4 and D5F3." (PMID 37120571, 2023).
tumor (continued). "Indeed, a recent study demonstrated that maintaining the monomeric state of EML4-ALK blocked its dimerization of the ALK TK domain, leading to the suppression of tumor growth both in vitro and in vivo." (PMID 36982897, 2023). "Hence, focused studies on the clinical relevance of TME localization patterns, as well as on the ALK-driven tumor cell interactions with their microenvironment are needed to further enhance our precision-medicine-based therapeutic strategies." (PMID 37511126, 2023). "Altogether, these results suggest that while comprehensive ctDNA analysis (i.e., using ΔVAFmean and Δt-MAD) remains superior for tumour monitoring in ALK + NSCLC, the information provided by serum cytokines, particularly of ΔIL-8, is independent and complementary to ctDNA mutational analysis data." (PMID 37120670, 2023). "Other factors that may have affected the detection sensitivity of ALK alterations are low tumor cell contents in some samples and spatial heterogeneity of genetic alterations within the tumor." (PMID 36807339, 2023). "Tumor cell proliferation could also be suppressed by the combination therapy with ALK-TKIs and afatinib, a pan-ErbB inhibitor." (PMID 37917191, 2023). "Another reason for higher IO efficacy in BRAF-mutant NSCLC, as opposed to EGFR or ALK, is the higher tumor mutational burden (TMB) and more frequent smoking status, as almost half of the BRAF-mutant NSCLC patients are found to be smokers." (PMID 37629023, 2023). "Although surgeries with negative margins are still considered the best approach, treatment for inoperable ALK- IMT may remain with traditional measures for neoplasms, such as chemotherapy." (PMID 37938503, 2023). "Immunohistochemical examination showed that the tumor cells were positive for ALK." (PMID 37656266, 2023). "The rearrangement of ALK causes pathological activation of the EML4 (echinoderm microtubule-associated-protein-like 4)-ALK complex, leading to alterations in the correct formation of microtubules and the proliferation and migration of tumor cells." (PMID 36836402, 2023). "However, the composition and cross-talk between the neoplastic cells and tumor microenvironment of ALK+ ALCL need further investigation." (PMID 37810974, 2023). "Interestingly, treatments with single-agent TNO155 or combinations with ALK-TKIs led to reduced cell invasion, and localized tumor shrinkage compared with untreated controls." (PMID 38032104, 2023). "The MES-like phenotype has been recently associated with resistance to ALK inhibitors (ALKi) due to the absence of ALK expression even in presence of tumour-driving ALK mutations, suggesting a role of ADRN-to-MES conversion in relapse." (PMID 37849756, 2023). "In recent decades, with the rapid development in tumor molecular biology, the mutations of the epidermal growth factor receptor (EGFR) and the abnormal fusion of the anaplastic lymphoma kinase (ALK) have been reported, which have been successfully applied in clinical settings as targeted therapies." (PMID 35734411, 2022). "The minimum number of tumor cells required for ALK ICC analysis is 200 as a cut-off." (PMID 35626451, 2022). "The immunohistochemical (IHC) results confirmed that the tumor was ALK fusion positive." (PMID 35978810, 2022). "Similarly, the phase I/II of alectinib and bevacizumab is recruiting (NCT02521051), and brigatinib and bevacizumab in a treatment-refractory setting (NCT04227028), as ALK is known to be a pro-angiogenic tumor." (PMID 36003760, 2022). "On the other hand, the absence of ALK mutation can indicate the development of resistance by the tumor, requiring ALK TKI combination therapy." (PMID 35211406, 2022).
tumor (continued). "In addition to plasma, ALK-positive tumor (n = 15) and normal lung tissue (n = 10) samples were subjected to cfMeDIP-seq." (PMID 36461127, 2022). "Ablative treatments such as SRS in the CNS, stereotactic body radiotherapy (SBRT) extracranially, radiofrequency ablation, cryotherapy, or surgery offer the promise of improved tumor control, tolerability, and convenience compared with conventional radiotherapy including in an ALK population." (PMID 36003760, 2022). "The induction of high expression of programmed cell death-Ligand 1(PD-L1) on the surface of tumor cells by ALK fusion genes may alter the tumor microenvironment, leading to the occurrence of tumor cell immune escape." (PMID 36591504, 2022). "Among 92 patients enrolled, circulating tumor DNA (ctDNA) was detected in 69 baseline samples (75%): 43 ALK fusions (62.3%) and two ALK mutations without fusion (2.8%)." (PMID 35437925, 2022). "However, the tumor response rate to crizotinib in the ALK‐rearranged cohort was also lower in the anticoagulation subgroup than in the non‐anticoagulated subgroup, and a similar trend was also observed in the cohort of ROS1‐rearranged NSCLC." (PMID 35510711, 2022). "We suggest that ALK expression reflects the origin of the tumor, the neuroendocrine crest." (PMID 35677534, 2022). "Aberrant ALK activation has been shown to sensitize tumor cells to pharmacologic ALK inhibition." (PMID 36337169, 2022). "Our study results showed significant associations between genetic variations and age (EGFR L858R), gender (EGFR exon 19 deletion, L858R), smoking history (EGFR L858R, exon 20 insertion, and KRAS mutation), histological type (EGFR exon 19 deletion, L858R), and tumor grade (ALK fusion)." (PMID 35061839, 2022). "In a clinical study of 25 patients who had various malignancies containing NTRK, ROS1, or ALK gene fuses and received an effective dose of entrectinib, an overall response rate of 79% with significant tumor regression in all NTRK-altered tumors (including ETv6: NTRK3 translocation) was observed." (PMID 35190738, 2022). "For NSCLC, activation of EGFR, ALK, ROS-1, and other targetable genes in the tumor are evaluated." (PMID 35806042, 2022). "In addition, chimeric antigen receptor (CAR-T) therapies and tumor vaccines targeting ALK rearrangements are under development." (PMID 35958559, 2022). "Furthermore, tumours can switch to ALK-independent growth through activation of “bypass” signalling pathways for growth and survival." (PMID 35884511, 2022). "Furthermore, in vivo imaging identified a role for ALK in the dynamic formation of 3D tumor spheroids." (PMID 35351152, 2022). "Besides, ALK inhibition induced immunogenic cell death in ALK-arranged cancer cells and conferred the protection of tumor rechallenge in the mouse model." (PMID 35062949, 2022). "Furthermore, tumors mitigate the cytotoxicity of ALK TKIs through a variety of mechanisms (ALK bypass substitution, autophagy, anti-apoptosis, etc), thereby reducing/eliminating their dependence on ALK signaling and promoting tumor cell survival." (PMID 35211406, 2022). "Single nucleotide variant analysis revealed low tumor mutational burden (<1 mutation per megabase) across all samples and absence of secondary ALK mutations." (PMID 35199053, 2022). "The TLS formation was negatively correlated with tumor progression in ALK+ tumors." (PMID 36233802, 2022). "Either decreased or increased tumor PD-L1 expression could be seen in different ALK+ LUAD cohorts or animal models." (PMID 36233802, 2022). "We now demonstrate that CD147 is essential for ALK+ ALCL tumor viability." (PMID 35676454, 2022). "In both patients, tumor cells displayed strong expression of ALK protein." (PMID 35144623, 2022). "This view could be extended to the MYCN and ALK oncogenes, because they are frequently mutated in NB, have a well-established influence on TME, and are pivotal targets of clinically evaluated anti-tumor therapies." (PMID 36231134, 2022).